INS (insulin)
Diseases named in the same sentence as INS in open-access papers (continued):
Sharing a sentence is not in itself a finding about the gene and the disease.
Hypoglycemia (continued). "Multiple daily injection insulin therapy frequently fails to meet hospital glycemic goals and is prone to hypoglycemia." (PMID 37578778, 2023). "Similarly, when the animals are dosed with insulin based on body weight for the insulin tolerance test, the HFD-fed rats respond most dramatically to produce hypoglycemia." (PMID 36472154, 2023). "In the VBAI group, there were 11 episodes of nonsevere hypoglycemia that were all autonomously handled by the VBAI with insulin dose reductions." (PMID 38039007, 2023). "These biochemical markers mainly include 3 types: non-ketogenic hypoglycemia; excessive secretion of insulin when blood glucose levels are low is required to increase the amount of glucose to avoid the occurrence of hypoglycemia." (PMID 36721237, 2023). "The use of SC instead of IV insulin, including during early stage of ICU stay, may have several explanations, such as less blood glucose measurements, reduced workload, and fear of hypoglycaemia or insulin dosing errors with continuous IV infusion." (PMID 37330419, 2023). "Our study confirms the results of previous studies showing that hypoglycemia during hospitalization, insulin-mediated or not, is a marker of short-term mortality." (PMID 38044455, 2023). "Alogliptin in combination with a specific dose of insulin, improved glycaemic control without elevating hypoglycaemia rates and without magnifying weight gain." (PMID 37287751, 2023). "Switching to premixed insulin, regardless of their previous basal insulin regimen, allowed many patients to achieve their HbA1c target without hypoglycemia in most cases." (PMID 37264625, 2023). "Two injuries occurred when parents failed to treat severe hypoglycemia and lethargy, and two were due to repeated failures to administer insulin at home properly." (PMID 38571735, 2023). "However, it has been reported that high doses of insulin are often required to overcome the elevated glucose set point in patients with GCK‐MODY, which resulted in frequent episodes of hypoglycemia." (PMID 36483860, 2022). "We showed that the epinephrine counterregulatory response to recurrent hypoglycemia is preserved in ketogenic diet-fed STZ-diabetic rats not supplemented with insulin." (PMID 36676967, 2022). "However, insulin supplementation is a double-edged sword for T1DM patients, as inappropriate insulin dosage can lead to severe hypoglycemia." (PMID 36147580, 2022). "This interesting finding reminds us to screen all diabetic patients for a history of hypoglycemia, rather than focusing only on those using insulin or insulin secretagogues." (PMID 36443872, 2022). "On the other side, the significant increase in basal insulin dose, not accompanied by any change in the time spent in hypoglycemia, possibly reflects a more confident self-titration." (PMID 35103951, 2022). "In terms of safety, the reduction of insulin units required for a low-carb diet played an important role in containing hypoglycemic events, with a halving of level II hypoglycemia compared to the previous diet and a total absence of severe hypoglycemic events." (PMID 35956384, 2022). "Generally, the usage of insulin preparations having long-lasting action as basal insulin leads to rare incidences of hypoglycemia, as opposed to the NPH insulin usage." (PMID 35723344, 2022). "The goal of glycemic management is lifetime euglycemia without hypoglycemia that undoubtedly requires glucose-regulated insulin replacement or secretion." (PMID 35178205, 2022). "In nondiabetic individuals, insulin secretion decreases and glucagon secretion increases to promote glycogenolysis and prevent hypoglycemia during aerobic exercise." (PMID 35345701, 2022). "Two others who experienced nocturnal hypoglycemia administrated an additional insulin bolus correction in the evening (9:45 pm – 10:00 pm) nonrelated to CHO supplementation." (PMID 36237197, 2022).
Hypoglycemia (continued). "Following oral administration in animalmodels,it showed a glucose-lowering effect by increasing UGE in a dose-dependentmanner, independently of insulin levels, without increasing the riskof hypoglycemia." (PMID 35924548, 2022). "Regarding β-cell function, although these knockout mice transiently exhibited neonatal hypoglycemia, levels of blood insulin and glucose were not significantly different in adult knockout mice from wild-type mice." (PMID 35005553, 2022). "However, most importantly, we have shown the ability of ricin to induce hypoglycemia despite STZ-induced β-cell destruction, suggesting that insulin plays little role, if any, in the development of ricin-induced hypoglycemia." (PMID 36548717, 2022). "The treatment guidelines for hypoglycemia recommends the use of 15–20 g of carbohydrates; however, the guidelines do not account for a reduction in insulin suspension by predictive low-glucose suspend (PLGS)." (PMID 35890301, 2022). "However, some investigators demonstrate that basal-bolus correction insulin regimen with glycemic target < 200 mg/dL in patients with ACS could lead to a hypoglycemic risk very close to zero (0.24%), with a significant reduction in hypoglycemia-related clinical events." (PMID 35629267, 2022). "In one study, the use of a fast-acting analogue (FIASP) administered at mealtime or post-meal, to cover a standardized liquid meal, compared with pre-meal rapid insulin analogues, led to better HbA1c results without increasing hypoglycemia." (PMID 36556278, 2022). "] which compared insulin degludec vs. glargine U100 for the incidence of general, nocturnal, and/or severe hypoglycemia." (PMID 36510287, 2022). "The separation between a dose that achieves normoglycemia and one that induces hypoglycemia is a fine line, one that practitioners prescribing insulin doses and those who take insulin are vexed with trying not to cross on a daily, on-going basis." (PMID 35177603, 2022). "The risk of hypoglycemia was comparable; DKA occurred in one participant receiving empagliflozin and this was associated with a nonfunctioning insulin pump." (PMID 35745754, 2022). "While children with COGHD often present hypoglycemic events and are very sensitive to the insulin tolerance test, hypoglycemia is not a feature of GHD in adults." (PMID 36557289, 2022). "Insulin use was associated with higher risks of mortality, HCC, cirrhotic decompensation, hepatic failure, cardiovascular events, and hypoglycemia than non-use of insulin." (PMID 35252271, 2022). "One article mentioned that parental support is necessary for the adjustment of insulin doses and also for the correction of any complications that may arise from the use of CSII, such as an eventual episode of severe hypoglycemia." (PMID 35183150, 2022). "Therefore, more vigorous blood glucose monitoring, and judicious use of insulin with a less stringent glycemic control should be the target to be achieved in patients with FCPD and hypoglycemia unawareness." (PMID 35819935, 2022). "But unfortunately, it increases the risk of weight gain and hypoglycemia, which are risk factors of T2DM, so the guidelines do not recommend insulin for all patients with T2DM." (PMID 36119737, 2022). "Despite less insulin, hemoglobin A1c improved, with reduced glycemic variability and no increase in hypoglycemia." (PMID 37908242, 2022). "In patients with T1DM and poor glycemic control in a basal-bolus insulin regimen, Subetta add-on therapy improved the glycemic profile without insulin dose intensification and without increasing the overall hypoglycemia rates." (PMID 35268481, 2022). "A recent study also found that certain oral anti-glucose agents such as glyburide are as safe and effective as insulin but not for the high rates of hypoglycemia in women with GDM." (PMID 35288489, 2022). "The study reported that 6 patients using insulin and getting IF had hypoglycaemia and its frequency was not different from control group." (PMID 36326405, 2022).
Hypoglycemia (continued). "It is postulated that the insulin dose has a greater influence on the duration of hypoglycemia than its type, but there is no clear position on this issue." (PMID 35324747, 2022). "The incidence of hypoglycemia < 4.0 mmol/L was 5 patients (0.4%) in the no insulin treatment group, 18 patients (2.8%) with bolus-only insulin, 53 patients (19.1%) with basal-bolus insulin, and 13 patients (13.3%) with premixed insulin." (PMID 34986826, 2022). "Although hypoglycemia in diabetic patients is frequently induced by insulin or hypoglycemic agents, hypoglycemia can occur in non-diabetic patients when they are hemodynamically unstable." (PMID 36079032, 2022). "Clinically, patients with DM treated with insulin exhibited left ventricular hypertrophy and greater diastolic dysfunction compared to patients without insulin prescription—possibly due to acute hypoglycemia induced by insulin therapy." (PMID 35369285, 2022). "If a patient has repeated hypoglycaemia, the rate of glycemic drop is more than 100 mg/dl/hour or hypokalaemia unresponsive to other management, the dose of insulin is decreased by half but never discontinued." (PMID 36102127, 2022). "These involve prolonging visits to the doctor, avoiding the predominant presentation of the adverse effects of the treatment (weight gain, hypoglycemia), and not presenting insulin as a punishment applied to the patient." (PMID 36556420, 2022). "We found the injected insulin was not degraded but recycled back to the circulation after the symptom of hypoglycemia in our patient." (PMID 36440205, 2022). "No dextrose:insulin ratio was found to protect against hypoglycemia, and 3/8 cats that became hypoglycemic had received ⩾2 g dextrose per unit of insulin." (PMID 36350735, 2022). "Fourth, we did not have data on the dose of insulin used, which can influence the occurrence of hypoglycemia." (PMID 36318703, 2022). "Whatever the method, individuals with T1D need alternate ways to raise glucagon (that have not been impacted by their condition) to better manage hypoglycemia as long as insulin delivery stays the same." (PMID 36992764, 2022). "A significant increase in wound healing rate (46.09 mm2/day vs. 32.24 mm2/day) was found in insulin treated patients independent of baseline wound size, again with no signs or symptoms of hypoglycemia." (PMID 35456892, 2022). "Compared with insulin alone, dapagliflozin 5 and 10 mg did not increase the incidence of severe hypoglycemia (OR = 1.1, 95% CI: 0.86 to 1.4 and OR = 1, 95% CI: 0.79 to 1.3)." (PMID 35872994, 2022). "Foetal relative liver weights (pooled for each litter) were similar between insulin-infused groups and controls irrespective of duration of hypoglycaemia." (PMID 35344549, 2022). "Other symptoms, which cannot be explained by neonatal diabetes (such as hypoglycemia without insulin, obvious enlargement of liver and spleen, electrolyte disturbance, normal range of HbA1c, etc.), and other metabolic diseases, were considered." (PMID 35757134, 2022). "Finally, recording hypoglycemia as a health problem in the EHR was low, although it was more frequent in patients receiving insulin." (PMID 36079064, 2022). "Of these 15 cats, seven developed hypoglycemia only after receiving an additional dose of insulin between hours 2 and 6, and thus their BGs were not analyzed further." (PMID 36350735, 2022). "Robust evidence on the productivity and utility of insulin-induced hypoglycemia is lacking in Canada." (PMID 35343912, 2022). "Authors reported that most people would consume supplementary CHO to avoid hypoglycemia during and in the hours following PA, regardless of insulin therapy (CSII or MDI) or CGM use." (PMID 36237197, 2022). "They had a higher rate of comorbidities, such as hypertension, CKD, and CVD, and the proportion of those using insulin, sulfonylurea, and glinides were higher compared with participants without severe hypoglycemia." (PMID 35195697, 2022).
Hypoglycemia (continued). "NICTH should be considered in non-diabetic patients who have recurrent hypoglycemia along with suppressed serum insulin and IGF-1 levels." (PMID 36211262, 2022). "They found an increase in median insulin antibody in the Exubera group, while a reduction of antibody in the subcutaneous group, however, the antibody did not correlate with HbA1c, hypoglycemia, and lung functioning." (PMID 35509734, 2022). "The reduction of glycemiclevels, in turn, leads to a lower percentage of protein glycation,enhanced insulin sensitivity of both liver and peripheral tissues,and improved functionality of insulin-producing pancreatic βcells, without inducing hypoglycemia." (PMID 35924548, 2022). "For example, closed-loop systems (the automated insulin delivery technology) do not allow users to register what is called “uncovered carbohydrates” that active people with T1D take without insulin bolus to avoid hypoglycemia during PA." (PMID 36420398, 2022). "The “global” impact of fetal hypoglycemia on pancreas growth and function, with both insulin and glucagon concentrations being diminished, were not expected, especially since fetal liver growth and IGF1 secretion were not affected." (PMID 36293384, 2022). "One patient experienced severe hypoglycemia while on insulin therapy in cycles 2 and 4, which were both not considered to be related to the study drug nor protocol procedures." (PMID 36013144, 2022). "The major objective is to povide superior glycemic control without increasing the rate of hypoglycemia and insulin dose." (PMID 35872994, 2022). "Factitious hypoglycaemia was excluded since the patient was unlikely to access insulin products under close supervision in our hospital." (PMID 36387920, 2022). "The study found an inverse relation between the emptying time from the gastric pouch, and plasma GLP-1 and insulin concentration with the meal, indicating that quicker transit time led to increases in insulin and GLP-1 plasma concentration and subsequent post-prandial hypoglycemia." (PMID 35399928, 2022). "Mild to moderate aerobic exercise has been associated with post-exercise hypoglycemia in T1DM, as the circulating insulin level does not drop at the start of exercise." (PMID 35345701, 2022). "Due to the increase in glucose tolerance with increased insulin secretion independent of insulin sensitivity, it is recommended to monitor the symptoms of hypoglycemia in concomitant use of hypoglycemic drugs such as metformin with SJW." (PMID 36246064, 2022). "Hypoglycemia is a possible complication of hypoglycemic drugs (especially insulin), and if not correctly diagnosed and treated, it can lead to death." (PMID 36359343, 2022). "All 174 subjects had adequate hypoglycaemia regardless of baseline fasting blood glucose level or insulin dose." (PMID 35465075, 2022). "One secondary objective of this study was to determine how much dextrose was required per unit of insulin to prevent development of hypoglycemia in this population of non-diabetic cats." (PMID 36350735, 2022). "The dawn phenomenon refers to an increase in blood glucose levels or a rise in the amount of insulin needed to maintain normoglycemia that occurs in the absence of antecedent hypoglycemia or waning insulin levels in the early morning." (PMID 35627961, 2022). "Appropriate carbohydrate intake and reduction of insulin doses compared to pre-pregnancy doses are important to maintain acceptable glycaemic control without hypoglycaemia in the breastfeeding period." (PMID 36432552, 2022). "Unlike specific diet, metformin, and sulfonylurea, induction of insulin in response to FFA1 agonists is attenuated when blood glucose levels are excessive, providing negative feedback that reduces the risk of hypoglycemia." (PMID 35213965, 2022). "Serum glucagon concentrations increased markedly (~16-fold) in both genotypes following insulin-induced hypoglycaemia compared to non-insulin treated mice." (PMID 35304577, 2022).
Hypoglycemia (continued). "Nocturnal hypoglycemia occurred more frequently in participants who administrated insulin bolus corrections in the evening with or without extra carbohydrate consumption." (PMID 36237197, 2022). "Among the other 38 patients with complete pathological information, 13 (34.2%) patients had no insulin-positive pNET, three of whom had recurrent hypoglycemia 8.33 ± 7.02 years after initial surgical cure." (PMID 35698198, 2022). "In a mouse model of type 1 diabetes, our hydrogel–micelle-composite insulin delivery device rapidly reduced blood glucose levels and kept them normal without hypoglycemia for around 24 h." (PMID 36559799, 2022). "High doses of LY2405319 did not induce hypoglycemia, which is an advantage compared to the current treatment with insulin, as overdosing insulin can result in hypoglycemic coma and death." (PMID 36699319, 2022). "This study showed that rescue treatment after insulin suspension in a situation of hypoglycemia only consisted of 9 g of carbohydrates with no repetition of carbohydrate treatments." (PMID 35890301, 2022). "Furthermore, this combination has less weight gain and hypoglycemia than insulin treatment alone because of the weight-losing effects of GLP-1 RAs and usually less insulin dosage needed to achieve better glycemic control compared with insulin treatment alone." (PMID 36559020, 2022). "Taken together, we posit that the benefits of MLF in hypoglycemia are due not to lowering glucose profiles directly but to its effects on the insulin signaling pathway, lipid metabolism, and the inflammatory response." (PMID 36278175, 2022). "A proposed local coverage determination from Centers for Medicare and Medicaid Services also would expand CGM coverage to those with a history of problematic hypoglycemia, regardless of insulin use." (PMID 36347498, 2022). "Keto-diet STZ-D groups were not supplemented with insulin due to profound hypoglycemia observed with insulin treatment (pilot experiments)." (PMID 36676967, 2022). "Glucose-responsive insulin delivery is the most-discussed solution for regulating blood glucose without inducing hypoglycemia." (PMID 35890174, 2022). "The coupling of insulin secretion to glucose concentration is not tightly regulated, leading to episodes of severe and recurrent hypoglycemia." (PMID 36237195, 2022). "The rate of hypoglycemia and glycemic control between NPH and premixed insulin regimens." (PMID 36149907, 2022). "The hysteresis model of glucose dependent insulin secretion thus does not appear to explain post-prandial hypoglycemia." (PMID 36148302, 2022). "Hypoglycaemia is a frequent complication of insulin therapy, but this serious adverse effect has not yet been systematically studied and is probably under-appreciated by most clinicians." (PMID 35552566, 2022). "We administered insulin intravenously to children and adolescents, and found moderate evidence that acute hypoglycemia does not result in a preferential shift towards high-carbohydrate foods." (PMID 36351679, 2022). "Mean time to hypoglycemia was approximately 17 min (±6.1 min), except for one participant who was already in hypoglycemia at the time of insulin administration (not detected at testing due to disparities between interstitial and venous glucose results)." (PMID 36351679, 2022). "The second form is more recent and occurs in nonobese patients with no history of hypoglycemia or ketoacidosis but who are underdosed with insulin." (PMID 35655318, 2022). "In waitlisted patients, the old paradigm that insulin should be the treatment of choice in the presence of severe liver dysfunction is no longer valid; novel antidiabetic agents may provide adequate glucose control without the risk of hypoglycemia, also offering cardiovascular protection." (PMID 34172646, 2022). "The closed-loop insulin delivery technique decreased the severity of overnight hyperglycemic incidents without inducing hypoglycemia." (PMID 35890301, 2022).